SCO1 (synthesis of cytochrome C oxidase 1)
Description:
Copper metallochaperone essential for the maturation of cytochrome c oxidase subunit II (MT-CO2/COX2). Together with SCO2, involved in delivering copper to the Cu(A) site on MT-CO2/COX2. Plays an important role in the regulation of copper homeostasis by controlling the abundance and cell membrane localization of copper transporter CTR1 (By similarity).
Synonyms: SCOD1; MC4DN4
Tractability: Small molecule: it has a high-quality binding pocket. Antibody: UniProt predicts a signal peptide or a membrane-spanning region. PROTAC: ubiquitination databases record sites on it; its protein half-life has been measured.
Gene: Protein-coding gene on chromosome 17 (10,672,474 to 10,698,375, reverse strand). Ensembl gene ENSG00000133028.
Subcellular location: Mitochondrion inner membrane
Pathways (Reactome):
Metabolism: Complex IV assembly
Gene Ontology:
Molecular function: protein binding; copper chaperone activity; copper ion binding
Biological process: mitochondrial respiratory chain complex IV assembly; intracellular copper ion homeostasis; respiratory chain complex IV assembly
Cellular component: mitochondrial inner membrane; mitochondrion; myofibril
Genetic constraint (gnomAD): Loss-of-function variants: 17 observed, 21.13 expected, observed/expected ratio (o/e) 0.8, 90% interval 0.55 to 1.21. The upper end of that interval is the gene's LOEUF score, 1.21, which puts it in group 5 of 6, group 1 being the genes least tolerant of losing a copy. Missense variants: 335 observed, 307.68 expected, observed/expected ratio (o/e) 1.09, 90% interval 1 to 1.19. Synonymous variants: 143 observed, 119.07 expected, observed/expected ratio (o/e) 1.2, 90% interval 1.05 to 1.38.
Gene-disease validity (ClinGen):
ClinGen rates the evidence that SCO1 causes each of these diseases.
mitochondrial disease (autosomal recessive): Definitive.
Homologues: Orthologues: chimpanzee SCO1 (99% identical), macaque SCO1 (95% identical), pig SCO1 (79% identical), dog SCO1 (77% identical), rabbit SCO1 (74% identical), mouse Sco1 (69% identical), rat Sco1 (68% identical), zebrafish sco1 (53% identical), Drosophila melanogaster Scox (42% identical), Caenorhabditis elegans sco-1 (35% identical). Paralogues in human: SCO2 (33% identical).
Diseases named in the same sentence as SCO1 in open-access papers:
SCO1 is named in the same sentence as 42 diseases in open-access papers, as found by Europe PMC text mining. Sharing a sentence is not in itself a finding about the gene and the disease. The quoted sentences say what the papers report.
developmental delay (3 papers, 2024 to 2025). "Defective SCO1 functioning would cause developmental delay and deterioration, seizures, cerebellar atrophy, and an increased susceptibility of hypothalamic and pituitary cells to energetic metabolism defects, leading to progressive deterioration of the hypothalamic–vascular–pituitary axis." (PMID 39214134, 2024). "TGex analysis (LifeMap Sciences, USA) prioritized 9 candidate variants across 7 genes (MED13, POGZ, SETBP1, SCN9A, SCO1, APTX, TIE1) associated with phenotypes including congenital megacolon, intellectual disability, motor delay, and developmental delays." (PMID 41195223, 2025).
Encephalopathy (3 papers, 2024). Encephalopathy is a term that means brain disease, damage, or malfunction. "Interestingly, another SCO1 missense mutation, which leads to a M294V substitution, was identified in a case of encephalopathy that was not as severe as those described previously and led the authors to propose a genotype–phenotype correlation with respect to SCO1 mutations." (PMID 38612624, 2024).
Hepatic failure (3 papers, 2018 to 2024). "For example, SURF 1 (Leigh-syndrome), SCO2 (hypertrophic cardiopathy), SCO1 (hepatic failure) and COX 10 (sensorineural hearing loss, anemia, and hypertrophic cardiomyopathy)." (PMID 30223867, 2018). "Surprisingly, adult Sco1hep mice exhibit a severe leukopenia and profound atrophy of the spleen; however, it is unclear whether these phenotypes are a direct consequence of ablating Sco1 expression in hepatocytes or a secondary consequence of liver failure." (PMID 36301669, 2023).
hypertrophic cardiomyopathy (3 papers, 2018 to 2024). A condition in which the myocardium is hypertrophied without an obvious cause. "SCO1 patients suffer from hypertrophic cardiomyopathy, neonatal hepatopathy, and ketoacidotic comas, whereas mutations in COA6 cause fatal infantile cardioencephalomyopathy." (PMID 29381136, 2018).
breast carcinoma (2 papers, 2016 to 2024). "One study suggested that miR‐663 reduced the expression of almost all OXPHOS assembly factors in breast cancer cells, including SCO1, and regulated the retrograde signal transduction from mitochondria to the nucleus, thus inhibiting the occurrence of breast cancer." (PMID 39676279, 2024). "We identified 13 members of the copper transport system associated with the occurrence, progression, and mortality of breast cancer, including SLC31A1, DMT1, ATP7A, ATP7B, MTs, GSH, ATOX1, CCS, COX17, SCO1, SCO2, and COX11." (PMID 39676279, 2024). "This is also supported by the increased expression of SLC31A1, SCO1, and COX11 mRNA observed in cell lines with a different tissue origin, such as MCF7 (breast cancer) and PC3 (prostate cancer)." (PMID 27516958, 2016).
Hepatic steatosis (2 papers, 2022 to 2024). Steatosis is a term used to denote lipid accumulation within hepatocytes. "Lastly, patients with SCO1 mutations (impacting complex IV assembly) display hepatic steatosis and elevated acyl-carnitines, suggesting a clinical overlap between mitochondrial ETC inhibition and ETF complex deficiency." (PMID 36154948, 2022).
hepatopathies (2 papers, 2015). "Likewise, SCO1 is involved in cellular copper homeostasis, and mutations in SCO1 cause a neonatal hepatopathy and ketoacidotic coma." (PMID 25875231, 2015). "Similarly, mutations causing distinct clinical phenotypes – cardioencephalopathies and hepatopathies – were found in two genes, SCO1 and SCO2, respectively, that are homologous to a yeast gene (SCO1) required for copper delivery into CIV." (PMID 26035862, 2015).
cerebral malaria (1 paper, 2019). A sequestration of Plasmodium falciparum in the brain, which can cause coma and/or seizures. "Further studies are needed to understand how the variants in SCO1 gene are associated with the pathological pathways of cerebral malaria." (PMID 31409341, 2019). "Deficiency of COX caused by mutations in SCO1 gene can lead to respiratory distress and severe metabolic acidosis which are also the major complications during cerebral malaria." (PMID 31409341, 2019).
colon carcinoma (1 paper, 2016). "Transcript‐level upregulation of SLC31A1,SCO1, and COX11 was also confirmed by the analysis of different colon carcinoma cell lines (Caco‐2, HT116, HT29) and cancer cell lines of different tissue origin (MCF7, PC3)." (PMID 27516958, 2016).
developmental and epileptic encephalopathy (1 paper, 2024). An epilepsy associated with developmental impairment that may be due to either the underlying etiology or the superimposed epileptic activity, or both. "We describe three patients with MC4DN4 with developmental and epileptic encephalopathy (DEE), hypopituitarism, and SCO1 pathogenic variants." (PMID 39214134, 2024).
diabetes (1 paper, 2010). "NDUFA5, NDUFS7, SCO1 and FMO4 all are involved in oxidative phosphorylation and have been shown to be important in diabetes." (PMID 20122255, 2010).
Failure to thrive (1 paper, 2024). Failure to thrive (FTT) refers to a child whose physical growth is substantially below the norm. "Animal models of SCO1 mutations have been subjected to organ-specific gene ablation for the liver or heart and show a growth restriction associated with failure to thrive." (PMID 39214134, 2024).
genetic hypopituitarism (1 paper, 2024). "Our findings expand knowledge of phenotypic variability in MC4DN4 and suggest that SCO1 is a candidate gene for genetic hypopituitarism and DEE." (PMID 39214134, 2024).
glioma (1 paper, 2023). A benign or malignant brain and spinal cord tumor that arises from glial cells (astrocytes, oligodendrocytes, ependymal cells). "Cytochrome c oxidase assembly factor 19(COX19) was involved in SCO1-dependent signaling essential for copper homeostasis, which was thought to be a risk factor in both gliomas and low-grade gliomas." (PMID 36882769, 2023).
hypopituitarism (1 paper, 2024). A condition of diminution or cessation of secretion of one or more hormones from the anterior pituitary gland. "Therefore, we suggest including pituitary function assessment in evaluations following diagnosis of MC4DN4 and considering SCO1 as a candidate gene in the diagnostic assessment of hypopituitarism and DEE." (PMID 39214134, 2024).
leukopenia (1 paper, 2023). "Hepatocyte-specific deletion of Sco1 triggers a progressive leukopenia and atrophy of the thymus and spleen." (PMID 36301669, 2023).
malaria (1 paper, 2022). Malaria is a serious and sometimes fatal disease caused by a parasite that commonly infects a certain type of mosquito which feeds on humans. "The mechanism of action of SCO1 in malaria pathogenesis is still unclear, but the differential expression of SCO1 regulating detoxification pathways of reactive oxygen species may contribute to Plasmodium control." (PMID 35646724, 2022).
ovarian carcinoma (1 paper, 2025). A malignant neoplasm originating from the surface ovarian epithelium. "Knockdown of LRPPRC in ovarian cancer cells is believed to impact the assembly of complex IV by decreasing SCO1, while simultaneously affecting the biosynthesis of complex IV through the downregulation of FDX1 and lipoic acidylated proteins." (PMID 41516324, 2025). "The possible reason could be the basal expression levels of LRPPRC and SCO1 differ between the ovarian cancer cell lines A2780 and SKOV3, with SKOV3 exhibiting lower expression levels." (PMID 41516324, 2025). "Following the knockdown of LRPPRC in two ovarian cancer cell types, we observed a reduction in the expression of chaperone proteins SCO1 and SCO2, with a more pronounced decrease in SCO1." (PMID 41516324, 2025). "Furthermore, it was found that inhibiting LRPPRC expression not only diminishes the translation of the core subunit MTCO1 of complex IV and the copper chaperone molecule SCO1 in A2780 and SKOV3 ovarian cancer cells, but also reduces the expression levels of FDX1 and LIAS." (PMID 41516324, 2025).
panhypopituitarism (1 paper, 2024). Insufficient production of all the anterior pituitary hormones. "We describe two siblings and a third unrelated patient with progressive panhypopituitarism and DEE in whom we identified homozygous missense SCO1 mutations." (PMID 39214134, 2024).
cancer (7 papers, 2014 to 2025). A tumor composed of atypical neoplastic, often pleomorphic cells that invade other tissues. "In this sense, the significant correlations between CTR1 (SLC31A1 gene), SCO1, and COX11 mRNA levels suggest that such transcriptional upregulation might be part of a gene regulation program associated with cancer proliferation." (PMID 27516958, 2016). "In particular, a correlated upregulation of SLC31A1, SCO1, and COX11 mRNA has been observed in cancer cells in vivo and in culture conditions." (PMID 27516958, 2016).
tumor (3 papers, 2012 to 2025). "UPRmt is closely associated with chemotherapy resistance in tumor cells, which may explain the significant decrease in SCO1 observed in SKOV3 cells." (PMID 41516324, 2025). "In the subnetwork related to tumor progression, the hubs from the blue module are the most connected, such as the genes Cmas, Kmt2a, Golt1b, Cdc34, Manf, Sco1, and Thoc3, followed by hubs from the light cyan (Extl2, Commd3, Wdr41, Keap1, Osbpl9) and pink modules." (PMID 32831131, 2020).
mitochondrial disease (1 paper, 2025). "Late detection of assembly factors with severe phenotype includes genes such as NDUFAF3, SURF1, TACO1, SCO1, LYRM7, or TIMMDC1, whose mutations are commonly found in patients with mitochondrial diseases (Fig. EV2F)." (PMID 40301572, 2025).
SCO1 also shares sentences with these, for which no sentence is quoted: colorectal cancer (2 papers); Leigh syndrome (2); anemia (1); Cerebellar atrophy (1); congenital megacolon (1); encephalomyopathies (1); Epileptic encephalopathy (1); genetic disorder (1); Intellectual disability (1); ischemia (1); lung carcinoma (1); metabolic acidosis (1); metabolic disorder (1); Motor delay (1); neurological diseases (1); osteosarcoma (1); prostate carcinoma (1); schizophrenia (1); sensorineural hearing loss (1); testis cancer (1).